SELP (selectin P)
Diseases named in the same sentence as SELP in open-access papers (continued):
Sharing a sentence is not in itself a finding about the gene and the disease.
hepatoma (4 papers, 2015 to 2025). "SelP expression is inducible by sodium selenite (100 nM, 24 h) in vitro in human hepatoma cells, where both mRNA and protein levels increase." (PMID 30571741, 2018). "For example, SelP expression is downregulated by TNFα stimulation of 3T3-L1 cells, by IL-6 in human hepatoma cells, and studies of the human SelP promoter have shown it is responsive to IL-1β, IFNγ and TNFα in HepG2 cells." (PMID 30571741, 2018). "As SelP is largely expressed in hepatocytes and secreted into the blood stream, we used human hepatoma HepG2 cells as a source of SelP." (PMID 26452064, 2015).
lung adenocarcinoma (4 papers, 2003 to 2022). A carcinoma that arises from the lung and is characterized by the presence of malignant glandular epithelial cells. "However, BMP2, SELP, and SLC6A4 were significantly down-regulated in lung adenocarcinoma cells compared with NHBE cells." (PMID 36147496, 2022). "Importantly, P-selectin-mediated binding of SCLC to endothelial cells has already been shown in vitro and the CD24/P-selectin pathway was found to initiate lung colonisation of the human lung adenocarcinoma cell line A125 in a mouse model." (PMID 12610508, 2003).
pancreatitis (4 papers, 2019 to 2026). Inflammation of the pancreas. "P-selectin plays a significant role in the adhesion and infiltration of neutrophils as inhibition of P-selectin has resulted in reduced damage and neutrophil infiltration in experimental pancreatitis." (PMID 38585277, 2024).
Autoimmunity (3 papers, 2017 to 2025). The occurrence of an immune reaction against the organism's own cells or tissues. "Thus, as for T cells, it appears that common mechanisms are shared between microglia in autoimmunity-related inflammation and cancer immunity and this inflammatory environment can be further enhanced by perturbation of the SELP-PSGL-1 axis." (PMID 33771989, 2021). "However, the role and the mechanisms in which SELP is involved in neurodegenerative and autoimmune disorders remain unknown." (PMID 33771989, 2021).
primary biliary cirrhosis (3 papers, 2015 to 2021). "Rs4679868 A and rs9852519T alleles (both in IL-12A) have been associated with increased risk of primary biliary cirrhosis whereas the A allele of rs6131 (SELP) has been found to lower platelet activation upon release of the cross-clamp in patients undergoing coronary artery bypass graft." (PMID 26396182, 2015).
small cell lung carcinoma (3 papers, 2016 to 2023). Small cell lung cancer (SCLC) is a highly aggressive malignant neoplasm, accounting for 10-15% of lung cancer cases, characterized byrapid growth, and early metastasis. "A study has shown that high selectin P expression is associated with metastasis of small cell lung cancer." (PMID 26975198, 2016).
Allergy (2 papers, 2010 to 2025). An allergy is an immune response or reaction to substances that are usually not harmful. "The analysis implicated a number of genes with roles in allergy and inflammation, including pro-inflammatory cytokines (IL1A, IL1B, IL6, IL8 and TNF) and factors involved in immune cell activation and recruitment (SELE, SELL, SELP, ICAM1, CSF2, CSF3, CCL2 and CXCL2)." (PMID 21067579, 2010).
anaphylaxis (2 papers, 2020 to 2022). An acute hypersensitivity reaction that occurs from exposure to an allergen. "Our validation work demonstrated the downregulation of six platelet‐related genes (TLN1, GATA1, SELP, SPARC, MPL and F13A1) in anaphylaxis patients compared with healthy controls." (PMID 36583159, 2022). "Six genes (GATA1 (P‐value = 2.52 × 10−2), SELP (P‐value = 1.86 × 10−2), MPL (P‐value = 2.72 × 10−2), F13A1 (P‐value = 1.62 × 10−2), SPARC (P‐value = 2.97 × 10−2) and TLN1 (P‐value = 6.13 × 10−3)) were significantly downregulated in anaphylaxis patients compared with healthy controls." (PMID 36583159, 2022). "Seven genes (TLN1, GATA1, SELP, GP1BA, MPL, F13A1 and SPARC) were also downregulated in patients with severe anaphylaxis who did not receive adrenaline before ED arrival, compared with healthy controls." (PMID 36583159, 2022).
Cachexia (2 papers, 2014 to 2020). Severe weight loss, wasting of muscle, loss of appetite, and general debility related to a chronic disease. "Remarkably, we observed similar results in the validation cohort of patients, showing that individuals who carry the AKT1-rs1130233-GG genotype or the C-allele of the SELP-rs6136 polymorphism were at reduced risk of developing cachexia." (PMID 25238546, 2014). "In particular, 44% of the patients harboring the SELP-rs6136-AA variants experienced cachexia, compared to 24% of the patients harboring the SELP-rs6136-AC/CC genotype." (PMID 25238546, 2014). "Therefore in the present study we evaluated the association of these candidate polymorphisms in the AKT1, IL6, and SELP genes with cachexia in a total population of 303 PDAC patients, in two independent cohorts." (PMID 25238546, 2014). "The SELP-rs6136 polymorphism was also significantly (p = 0.011) associated with cachexia." (PMID 25238546, 2014). "The association of SELP-rs6136, IL6-rs1800796 and AKT1-rs1130233 polymorphisms with cachexia as well as the correlation between cachexia and the candidate polymorphisms and overall survival were analyzed." (PMID 25238546, 2014). "To investigate whether there is an association between cachexia and IL6-rs1800796, AKT1-rs1130233 and SELP-rs6136 polymorphisms, we performed genotyping using genomic DNA extracted from peripheral blood samples." (PMID 25238546, 2014). "Therefore, in the current study we investigated the association with cachexia and the prognostic value of the candidate functional polymorphisms IL6-rs1800796, AKT1-rs1130233 and SELP-rs6136 in a first cohort of 151 patients with locally-advanced or metastatic PDAC." (PMID 25238546, 2014).
diabetic retinopathy (2 papers, 2017 to 2020). "Additionally, SELP rs6128 major allele is associated with a higher sP-selectin concentration and diabetic retinopathy." (PMID 28646244, 2017).
Hepatitis (2 papers, 2021 to 2024). Inflammation of the liver. "To evaluate the effectiveness of drug delivery via the P-selectin–PSGL-1 axis in vivo, we used the TAA-induced hepatitis mouse model." (PMID 39513885, 2024).
nasopharyngeal carcinoma (2 papers, 2018 to 2023). A carcinoma arising from the nasopharyngeal epithelium. "Through bioinformatic analysis, we found that these DElncRNAs and SELP are down-regulated in nasopharyngeal carcinoma." (PMID 36447000, 2023).
osteoporosis (2 papers, 2022 to 2023). A condition of reduced bone mass, with decreased cortical thickness and a decrease in the number and size of the trabeculae of cancellous bone (but normal chemical composition), resulting in increased fracture incidence. "In agreement with this function, we found P-selectin-positive EVs in OVX-induced osteoporosis, in which the involvement of leukocyte activation and inflammation is well elucidated." (PMID 36282293, 2023). "In the present report, WGS of a two-generation Maltese pedigree with early-onset familial osteoporosis and low BMD identified three rare and evolutionary conserved missense variants within SELP (c.2177T>C), TGF-β2 (c.1136C>T) and ADAMTS20 (c.4090A>T)." (PMID 35205249, 2022). "In conclusion, this report has described three rare missense variants in SELP, TGF-β2 and ADAMTS20 that alone or in combination could potentially be the underlying genetic determinant(s) contributing to early-onset familial osteoporosis and low BMD in the two-generation Maltese pedigree." (PMID 35205249, 2022).
pulmonary hypertension (2 papers, 2020 to 2023). Increased pressure within the pulmonary circulation due to lung or heart disorder. "The results showed that the ratios of P-selectin-positive platelets in non-pulmonary hypertension patients, PAH patients, and CTEPH patients were 1.40%, 2.40%, and 2.63%, respectively (non- PH vs. CTEPH, p < 0.01)." (PMID 36984870, 2023).
selenium deficiency (2 papers, 2023 to 2025). A nutritional deficiency disease resulting from inadequate selenium levels in the body, which can lead to impaired function of selenoproteins essential for antioxidant defense and thyroid hormone metabolism. "Consequently, dysregulation of GPx3 and SelP has been implicated in various pathological conditions related to oxidative stress and selenium deficiency." (PMID 40429666, 2025). "Thus, the SelP evaluation may offer a marker of selenium deficiency." (PMID 40429666, 2025).
urticaria (2 papers, 2018 to 2023). A vascular reaction of the skin characterized by erythema and wheal formation due to localized increase of vascular permeability. "We found significant trans-pQTL associations of the GCSAML urticaria-associated variant with plasma levels of five proteins encoded by TPSAB1, TPSB2, KIT, SELP, and SIGLEC6 (P-values < 1.0 × 10−7)." (PMID 37430141, 2023).
abortion (1 paper, 2017). the ending of pregnancy by removing a fetus or embryo before it can survive outside the uterus. "An excessive up-regulation of pro-inflammatory cytokines can trigger abortion in mice and both SELP and PSGL1 have been implicated." (PMID 28419109, 2017). "SELP is also up-regulated in decidual endothelial cells of women suffering spontaneous abortion." (PMID 28419109, 2017).
childhood cancer (1 paper, 2022). "We identified novel genetic variants in the SELP gene and HLA region associated with EAA-Horvath and EAA-Hannum, respectively, among survivors of childhood cancer." (PMID 35313970, 2022). "In summary, we identified novel genetic variants in SELP gene and HLA region associated with EAA-Horvath and EAA-Hannum, respectively, among survivors of childhood cancer." (PMID 35313970, 2022).
geographic atrophy (1 paper, 2011). "Patients were divided into AMD subgroups (dry AMD, wet AMD, and geographic atrophy and further analyzed for associations with the SNPs in SELE, SELL, and SELP." (PMID 21521525, 2011).
ischemic disease (1 paper, 2025). Lack of blood supply to an area of the body, resulting in impairment of tissue oxygenation. "P-selectin plays a multifaceted role and promotes microvascular thrombosis and angiogenesis caused by ischemic diseases such as cardiovascular, inflammatory bowel, and septic diseases." (PMID 40699808, 2025).
kidney cancer (1 paper, 2024). Primary or metastatic malignant neoplasm involving the kidney. "Several genes showed a low gDS in most kidney cancer cell lines, such as CD82, CD7, MEST, SELP, BMP6, CA2, DNAJC6, and VEPH1." (PMID 38728235, 2024).
medulloblastoma (1 paper, 2023). A malignant, invasive embryonal neoplasm arising from the cerebellum. "Targeting of tumour vasculature endothelial P-selectin promotes caveolin-1-mediated transcytosis for enhanced blood–brain barrier crossing of therapeutic nanoparticles against medulloblastoma." (PMID 36864161, 2023).
nasal polyps (1 paper, 2014). "E- and P-selectin positive cells were detected in the endothelium of nasal polyps and inferior turbinates (n = 10)." (PMID 24995349, 2014).
Osteopenia (1 paper, 2022). Osteopenia is a term to define bone density that is not normal but also not as low as osteoporosis. "The SELP c.2177T>C variant was present in heterozygosity in the three osteoporotic male siblings (III1, III4, III5), as well as relatives II4, II5, II11 and III10, all of whom had mild osteopenia at the LS or a history of a low-trauma wrist fracture (in the case of II4)." (PMID 35205249, 2022).
Splenomegaly (1 paper, 2017). Abnormal increased size of the spleen. "We have observed that the absence of P-Selectin promotes splenomegaly with reduced naïve T cell population, elevated activated/effector T cell subset, increased germinal center B and Tfh populations and high production of autoreactive antibodies." (PMID 28150814, 2017).
tumor (402 papers, 1998 to 2026). "Thus, the direct association of tumor cells with platelets through a P-selectin-PSGL-1 interaction is sufficient to mediate the deposition of a fibrin clot on the surface of tumor cells." (PMID 33042789, 2020). "Activated platelets and endothelial cells express SELP on their surface, which enables the binding of tumour cells, leading to cell aggregation and promoting blood clotting." (PMID 41528397, 2026). "P-selectin promotes the arrest of tumor cells in the vascular endothelium by mutual recognition with the P-selectin glycoprotein ligand-1 (PSGL-1) or CD44 receptor on the surface of tumor cells and contributes to tumor cell metastasis." (PMID 39852571, 2025). "In contrast, Venous‐1 cell subsets express the specific endothelial cell genes IL‐33, MADCAM1, SELP, and SELE, which are closely associated with leukocyte adhesion, angiogenesis, and tumor progression." (PMID 40860436, 2025). "On one side, SELP is reported to facilitate leukocyte recruitment to the site of inflammation, potentially contributing to thrombosis, tumour progression and cancer cachexia." (PMID 39768338, 2024). "In particular, L-Selectin promotes myeloid cell recruitment and P-Selectin helps tumor cell adherence through platelet-tumor cell interactions." (PMID 39717751, 2024). "Another important finding relates to SELP, a crucial mediator of endothelial integrity and tumour angiogenesis." (PMID 39768338, 2024). "P-selectin promotes the generation of platelet—tumor cell complexes in the circulation and stimulates extravasated into a distant site." (PMID 37626742, 2023). "Anti-SELP therapy holds potential for enhancing tumor sensitivity to immunotherapeutic approaches and conventional radiotherapy treatments." (PMID 37700840, 2023). "Tumor growth inhibition provided by SeMet can be due to SelP antioxidant activity in the plasma since this group presented the highest blood Se concentration." (PMID 36634075, 2023). "P-selectin plays a key role in tumor proliferation, angiogenesis, and EMT by acting as a platelet molecular switch to promote platelet adhesion and aggregation." (PMID 35936717, 2022). "As SELP is known to be expressed by activated tumor endothelial cells, we co-stained for SELP and CD31 in two human and one murine GB mouse samples (Supplementary 3D)." (PMID 33771989, 2021). "Immunostaining of these samples, demonstrated higher expression of SELP in STS tumor samples compared to LTS tumors or normal brain samples." (PMID 33771989, 2021). "SELP was found to be expressed by PD-GB4 tumor spheroids, and its level of expression was increased when the spheroids were treated with microglia CM as demonstrated by flow cytometry." (PMID 33771989, 2021). "Glycosaminoglycans, for instance LMWH, that block the plasmatic coagulation cascade and interfere with P-selectin potentially provide an advantage for inhibition of tumor cell induced platelet activation as compared with DOACs." (PMID 32110917, 2020). "The previous study evaluated the low expression of P-selectin protein correlated with diminished leukocyte tumour infiltration and poor prognosis." (PMID 31877723, 2019). "Taken together, our results from two different experimental settings indicate that P-selectin potentiates tumor growth likely by mediating platelet adhesion to tumor cells." (PMID 25762641, 2015). "As the functional role of HPA-binding glycotopes present on the tumour cells is the focus of this study, we focused on E- and P-selectin present on the host endothelia serving as possible binding partners for HPA-positive cancer cells." (PMID 20010946, 2010). "Overexpression of ALYREF and YBX1 was accompanied by the upregulation of immune checkpoint inhibitors (such as CD276 and PDCD1) and downregulation of immune checkpoint stimulants (such as CX3L1, ITGB2, CD40LG and SELP), which promoted evasion of immune surveillance by these tumor cells." (PMID 38238581, 2024).
tumor (continued). "Similarly, cell adhesion molecules, such as ICAM1 and SELP, also showed distinct expression patterns across the subgroups, implying potential differences in immune cell recruitment and interaction within the tumor microenvironment." (PMID 39711402, 2024). "The present study aimed to investigate whether dietary Se supplementation affected 4T1 tumoral volume associated with blood Se concentration, hepatic GPx-1 activity and SelP expression, and tumor and metastatic histomorphology." (PMID 36634075, 2023). "Similarly, another study also identified two types of tumor ECs: INSR+ tumor EC (INSRhiHSPG2+PLVAP+) and ACKR1+ tumor EC (ACKR1+SELP+IL1R1+) in early-stage lung cancer that radiologically manifests as part-solid nodules." (PMID 37187731, 2023). "The rapid mobilization of P–selectin primarily to TCIPA was observed in tumor blood vessels in different speciessuch as oil miceC57BL6 miceand nude miceand in different tumor types like lung carcinomacolon carcinomabreast carcinomaand gliomas in response to radiotherapy." (PMID 35814405, 2022). "Furthermore, P-selectin promotes tumor metastasis by functional inhibition of CD4+ and CD8+ T cells via infiltration of regulatory T cells and aggregation of other cells." (PMID 35936717, 2022). "Likewise, blocking SELP function was accompanied by delayed tumor growth, prolonged survival, and improved immune infiltration in vivo." (PMID 36497232, 2022). "As expected, we also found positive staining of SELP on the tumor blood vessels." (PMID 33771989, 2021). "Indeed, our results show that blocking SELP function leads to delayed tumor growth, prolonged survival and improved immune infiltration in vivo." (PMID 33771989, 2021). "Thus, we show that specific inhibition of SELP using both molecular and pharmacological agents delayed tumor progression." (PMID 33771989, 2021). "In contrast to the contribution of P-selectin positive platelets, leukocyte L-selectin can facilitate tumor metastasis at later stage, as L-selectin mediates the leukocyte recruitment to tumor emboli after P-selectin-mediated platelet-cancer cell aggregates are formed." (PMID 28680883, 2017). "Because P-selectin is expressed on the stimulated endothelial cells and activated platelets, exploring whether only platelet P-selectin plays an important role in tumor growth is important." (PMID 25762641, 2015). "Since P-selectin is found within the Weibel-Palade bodies of endothelial cells and α-granules of platelets, CS-E on tumor cells may facilitate metastasis by binding to P-selectin present in endothelial cells and/or platelets." (PMID 23349846, 2013). "Consequently, increased SELP levels can promote tumour metastasis and VTE development." (PMID 41528397, 2026). "The observation that SELP is expressed by GB cells in vitro and in vivo, and overexpressed in the presence of microglia, prompted us to further investigate the functional role of SELP in GB progression, and specifically in GB cell-microglia (tumor-host) interactions." (PMID 33771989, 2021). "Since inhibition of SELP did not cause direct tumor-killing, combining anti-SELP treatment with the standard chemotherapy (TMZ) may be beneficial." (PMID 33771989, 2021). "The first niche, predominantly observed in patients responding positively to immunochemotherapy, is characterized by the notable presence of SELP+ HEV-like vessels and a dense population of APOD+ myCAFs within the tumor recovery zones." (PMID 40107247, 2025). "Compared to other EC subtypes,EC4 exhibited elevated expression levels of multiple genes implicated in antigen presentation (HLADRB1,HLA-DRB5,and HLA-DRA),immune cell recruitment (SELP,LIFR, and ACKR1),and anti-tumor inflammation (CCL14,IFITM1)." (PMID 41394809, 2025). "Collectively, these findings emphasize the critical roles of SELP+ HEVs and APOD+ myCAFs in facilitating T/NK cell infiltration and enhancing antigen presentation, thereby contributing to effective tumor regression." (PMID 40107247, 2025).